NRAS (NRAS proto-oncogene, GTPase)
Diseases named in the same sentence as NRAS in open-access papers (continued):
Sharing a sentence is not in itself a finding about the gene and the disease.
hepatocellular carcinoma (27 papers, 2017 to 2025). A malignant tumor that arises from hepatocytes. "NRAS has been verified associated with the erastin resistance in hepatocellular carcinoma, however, whether ferroptosis pathway is involved in this effect needs to be further clarified." (PMID 34671612, 2021). "This study provides novel insights into the mutational patterns of the AKT1 and NRAS genes in Egyptian patients with hepatocellular carcinoma (HCC)." (PMID 41291320, 2025). "In particular, the delivery of the pan‐RASOFF DARPin K27 formulated in LNPs resulted in a reduction of tumor load in a NRAS‐mutant hepatocellular carcinoma model." (PMID 40517320, 2025). "In hepatocellular carcinoma, NRAS expression is markedly upregulated in hepatocellular carcinoma tissues and cell lines; the combined inhibition of KRAS and NRAS reduces the resistance of hepatocellular carcinoma to sorafenib." (PMID 35339759, 2022). "At this point, the majority of NRAS-injected Cox2-knockout animals develop macroscopic liver tumors with microscopic features of hepatocellular carcinoma (HCC), whereas most NRAS-injected animals with normal Cox2 function have no tumors." (PMID 33730589, 2021). "The circRanGAP1/miR-27b-3p/NRAS axis can promote the progression of hepatocellular carcinoma." (PMID 38082189, 2024). "These included the well-established NRAS activating mutation Q61L, which fully explains the constitutively elevated ERK phosphorylation and the insensitivity to the effects of the dominant negative H-Ras17N mutant that we observed in HepG2 hepatoma cells." (PMID 32694512, 2020). "A recent study showed that overexpression of oncogenic NRAS (G12V) alone is enough to induce hepatocellular carcinoma (HCC) in mice." (PMID 40943262, 2025). "Notably, circRanGAP1 functions as a target of miR-27b-3p and may promote the onset of hepatocellular carcinoma (HCC) through the miR-27b-3p/NRAS/ERK axis." (PMID 38539937, 2024). "Its mutations are associated with several cancers, including hepatocellular carcinoma (HCC), wherein the RAS/MEK/ERK pathway facilitates tumor proliferation by activating NRAS." (PMID 41291320, 2025). "Besides, sustained activation of oncogene signaling such as RHO GTPase related signaling, HGF/c-MET signaling, PI3K/AKT signaling, NRAS/ERK signaling, is a key driver of hepatocellular carcinoma (HCC) progression." (PMID 38254216, 2024).
ovarian carcinoma (27 papers, 1998 to 2025). A malignant neoplasm originating from the surface ovarian epithelium. "According to the literature, in advanced ovarian carcinomas, NRAS mutations are rare." (PMID 39456660, 2024). "It determined the VAF of ovarian cancer‐related mutations KRAS‐G12R, NRAS‐G12C, and BRAF‐V600E in both tissue and blood samples (n = 77), discriminating cancer patients and healthy individuals with significant difference (p < 0.001)." (PMID 39903775, 2025). "One of the histological and molecular subtypes of ovarian cancer is low-grade serous (LGS) ovarian carcinoma characterized by BRAF, KRAS, NRAS and ERBB2 mutation, amplification or overexpression." (PMID 25408231, 2014). "Interestingly, the mutation rates for commonly reported genes in ovarian cancer such as RB1, PTEN, PIK3CA, NRAS, KRAS, and BRAF were below 3% in the entire cohort." (PMID 33016563, 2021). "Among disease entities with more than 10 patients tested, no NRAS mutations were found in ovarian cancer, and squamous cell carcinoma of head and neck." (PMID 21829508, 2011). "Our method also determined the VAF of ovarian cancer‐related sites (KRAS‐G12R, NRAS‐G12C, and BRAF‐V600E) in clinical tissue and blood samples, enabling the discrimination between ovarian cancer patients and healthy volunteers." (PMID 39903775, 2025).
bladder cancer (24 papers, 2009 to 2024). "We have therefore developed a multiplex mutation assay for the detection of the most frequently occurring HRAS, KRAS, and NRAS mutations in bladder cancer." (PMID 21072204, 2010). "The evidence is also available that TP63+ bladder cancers, which all bear either HRAS or NRAS mutations, are particularly sensitive to RAF1 pathway inhibition." (PMID 39678505, 2024). "Previous study showed that mutations in HRAS, KRAS, and NRAS exist in approximately 30% of human cancers, with HRAS mutations being more common in bladder cancer compared to the other two67." (PMID 37704624, 2023). "In contrast, 27.2% of HRAS-mutant bladder cancers carried a co-altered MAPK mutation compared to 23% and 44% of KRAS and NRAS, respectively." (PMID 37503077, 2023). "The KEGG bladder cancer pathway activation in poor prognosis CRCs was mostly due to increased expression of functional nodes HRAS/KRAS/NRAS, ARAF/BRAF/RAF1, MAPK1/MAPK3, and RPS6KA5." (PMID 36316649, 2022). "Our observations indicate a good therapeutic window for PI3K inhibitors in some bladder cancers that harbor PI3K hotspot mutations, as well as those with co-existing NRAS mutations." (PMID 27465249, 2016). "In KEGG bladder cancer pathway, the oncogenes NRAS and ERBB2 were found up-regulated, hypothetically, due to lower of expression of miR-28-5p and miR-125b, respectively." (PMID 23717626, 2013). "RAS is the most frequently mutated oncogene in bladder cancer, with KRAS, HRAS, and NRAS involved." (PMID 39678505, 2024). "We also identified the RAS oncogene family (KRAS, NRAS, and HRAS) as a bladder cancer stimulus factor." (PMID 34234808, 2021). "This study has discovered that miRNA-1184 interacts with KRAS, NRAS, and HRAS coding genes, thereby regulating their effect in bladder cancer." (PMID 34234808, 2021). "This pathway is activated in around 40% bladder cancer cases (FGFR3: > 10%, EGFR:> 10%, ERBB2:~ 10%, ERBB3:~ 10%, NRAS/HRAS/KRAS:~ 10%, PTEN: ~ 10%, AKT3:~ 10%)." (PMID 31665050, 2019). "Additionally, NRAS, EHD4, ITGB1 and MUC1, which were among the protein set correlating with bladder cancer on PCA, have been found in various studies of bladder cancer exosomes." (PMID 32249794, 2020). "Furthermore, the oncogenes NRAS and ERBB2 are up-regulated in bladder cancer, hypothetically, due to lower of expression of miR-28-5p and miR-125b, respectively." (PMID 23717626, 2013).
glioblastoma (24 papers, 2012 to 2025). The most malignant astrocytic tumor (WHO grade IV). "In glioblastoma, NRAS activation could be caused by a direct mutation (5%) or by other alterations, such as amplification, overexpression of growth factor receptor or aberrations in other RAS pathway genes." (PMID 26799668, 2016). "They found a NRAS mutation in 11 oligodendrogliomas, 2 KRAS mutations in 16 anaplastic oligodendrogliomas, and 2 KRAS mutations and 2 NRAS mutations in 226 glioblastomas." (PMID 34525976, 2021). "HER2 gene amplification has been shown in glioblastoma multiforme in correlation to KRAS and NRAS mutations." (PMID 31952211, 2020). "This latter exerts a tumor suppressive function by inhibiting proliferation and malignancy of glioblastoma cells by targeting both NRAS and KRAS and by modulating microglia activation through TLR7." (PMID 33287106, 2020). "We identified NRAS mRNA as a critical, direct target of miR-340: in fact, miR-340 negatively influenced multiple aspects of glioblastoma tumorigenesis by down-regulating NRAS and downstream AKT and ERK pathways." (PMID 26799668, 2016). "NRAS is among the oncogene targets of miR-124 in glioblastoma and its signaling pathway plays a crucial role in many cancers by regulating cell proliferation, differentiation, and survival." (PMID 26041995, 2015). "We also examined the expression of NRAS in glioblastoma stem cells and neural stem cells, where miR-124 exhibits differential expression." (PMID 22558405, 2012). "A significant increase of NRAS mRNA expression was detected in glioblastoma stem cells, compared to neural stem cells." (PMID 22558405, 2012). "Since EIF4A3 is involved in various RNA metabolic processes, including nonsense-mediated RNA decay and RNA splicing, for example, EIF4A3-induced circular RNA ASAP1 (circASAP1) facilitates tumorigenesis and temozolomide resistance of glioblastoma via NRAS/MEK1/ERK1/2 signaling pathway." (PMID 34408982, 2021). "Interestingly, 6-thio-dG and Gamitrinib triggered significant death of NRAS-mutant SKNAS glioblastoma cells, as single agents or in combination." (PMID 29695835, 2018). "Thus, we demonstrate that expression of miR-340 in glioblastoma is responsible for a strong tumor-suppressive effect in LTS patients by down-regulating NRAS." (PMID 26799668, 2016). "Next, we tested whether miR-124 targets NRAS expression in glioblastoma stem cells." (PMID 22558405, 2012). "circASAP1 overexpression promotes glioblastoma cell proliferation and TMZ resistance via the circASAP1/miR-502-5p/NRAS regulatory network, indicating that circASAP1 is a potential target for TMZ-resistant glioblastoma therapy." (PMID 35070998, 2021). "Still, in case of glioblastoma multiforme, HER2 was identified to be a part of cluster 1 also involving other top hub nodes of proto-oncogenes KRAS, HRAS and NRAS." (PMID 31952211, 2020). "Mutations identified in the radiation-associated DIPGs had significant molecular overlap with recurrent drivers of adult glioblastoma (e.g. NRAS, EGFR, and PTEN), as opposed to epigenetic dysregulation in H3-driven primary DIPGs." (PMID 30049282, 2018). "Furthermore, using the Targetscan algorithm, we predicted oncogenes NRAS and PIM3 as putative target genes of miR-124, one of the down-regulated miRNAs in glioblastoma stem cells." (PMID 22558405, 2012).
papillary thyroid carcinoma (24 papers, 2013 to 2025). "BRAF mutations are strongly linked to malignant transformation, whereas NRAS mutations are more commonly associated with the follicular variant of papillary thyroid cancer." (PMID 41356641, 2025). "Thyroid nodules with GEA and low-risk mutations such as HRAS or NRAS are significantly more likely to be low-grade malignancies such as a follicular variant of papillary thyroid carcinoma." (PMID 36612045, 2022). "Some authors have also suggested the role of NRAS exon 61 mutation in the progression of PDTC from well-differentiated thyroid carcinoma and TERT-p mutations as the most common alterations in PDTC." (PMID 35892838, 2022). "NRAS mutations (in codon 61) were found in 2 other cases with papillary thyroid cancer (4%; 1 case with follicular variant)." (PMID 28493027, 2017). "Mutations of BRAF (B-type Raf kinase) were detected in 23 and mutation of NRAS (Neuroblastoma RAS Viral Oncogene Homolog) in 2 papillary thyroid cancers." (PMID 28493027, 2017). "Mutations of BRAF, KRAS, and NRAS were tested in tissue samples of 53 patients (39 papillary thyroid cancers, 10 with follicular variant; 3 follicular thyroid cancers, 1 oxyphilic variant)." (PMID 28493027, 2017). "In particular, our data strongly support that the PDTC subtype—as defined by Turin consensus criteria—is separate even molecularly from the other high-grade differentiated thyroid cancers, mainly because of the high prevalence of NRAS mutations and the extremely low prevalence of BRAF mutations." (PMID 41123735, 2025). "This study was designed with the aim of examining the relationship between clinicopathological characteristics and mutations in the BRAF, HRAS, KRAS, and NRAS genes with metastatic disease and RAIR development in patients with differentiated thyroid cancer." (PMID 40104288, 2025). "In comparison, BRAF p.V600E occurs in over 50% of adult papillary thyroid carcinoma (PTC) and NRAS/HRAS/KRAS mutations in 30-45% of follicular thyroid cancer and follicular variant PTC." (PMID 39558957, 2024). "BRAFV600E, KRAS variants, NRAS variants, and HRAS variants have also been observed in papillary carcinoma originating from struma ovarii." (PMID 36975488, 2023). "Thyroid follicular cells of patients with differentiated thyroid cancer (DTC) were considered to have a higher number of IGF-1 binding sites, and increased frequency of NRAS codon 61 point mutations was determined in DTC patients with acromegaly." (PMID 36945936, 2023). "RET/PTC rearrangement, BRAF, NRAS, and KRAS mutations are considered to be mutually exclusive in papillary thyroid carcinoma." (PMID 28493027, 2017). "We analyzed mutation status of BRAF and RAS (HRAS, NRAS, and KRAS) oncogenes in 34 papillary thyroid cancer samples using MALDI-TOF-MS." (PMID 24367375, 2013). "The aim of this study was to investigate the relationship between the presence of the BRAF, HRAS, NRAS, and KRAS gene mutations and the development of dedifferentiation (iodine-refractory disease) and extrathyroidal disease in patients with differentiated thyroid carcinoma (DTC)." (PMID 40104288, 2025). "The mutual exclusivity of the NRAS, HRAS, and BRAF mutations in THCA tumors has been interpreted to mean that these mutations must have interchangeable effects on MAPK signaling activation, the main cancer-driving event in papillary thyroid carcinomas." (PMID 29125844, 2017). "No mutations of BRAF and NRAS were found in 28 cases (53%; 16 patients with papillary thyroid cancer, 8 patients with follicular variant; 3 patients with follicular thyroid cancer, 1 patient with oxyphilic variant)." (PMID 28493027, 2017). "In a study that included 14 patients with differentiated thyroid cancer (DTC), the most common genetic alteration was in the NRAS codon 61, whereas BRAF V600E was less frequent." (PMID 37374352, 2023).
papillary thyroid carcinoma (continued). "We compared the ERK score, a measure of ERK activity derived from RNAseq data, from RET-rearranged, BRAF mutant, and RAS mutant papillary thyroid cancers in TCGA patients, and we found that RET-rearranged cancers have significantly higher ERK scores than either BRAF or NRAS/HRAS mutant tumors." (PMID 35510953, 2022).
liver cancer (23 papers, 2014 to 2025). An epithelial or non-epithelial malignant neoplasm that arises from the liver. "In mice, hydrodynamic tail vein injection of pre-miR-107 or anti-Kif23 shRNA effectively inhibited c-Myc-NRAS-induced aggressive liver cancer, highlighting miR-107/KIF23 as a potential therapeutic target." (PMID 40546347, 2025). "In the current study, we mainly used the SB-HDTVI-based Akt-YAP1 and Akt-NRAS HC-derived cHCC-CCA models to investigate the roles of Sox9 in the liver cancer setting, including cHCC-CCA." (PMID 39273023, 2024). "All CWT mice developed a significant burden of liver cancer, with liver LW/BW reaching 30 for Akt-NRAS and 8 for Akt-YAP1 animals, respectively." (PMID 39273023, 2024). "To evaluate the role of NEAT1 in mTORC1-dependent aerobic glycolysis, liver tumor development and therapy in vivo, we generated mAKT/NRAS-driven mouse liver cancer by hydrodynamic transfection (HDT) in the absence or presence of shNeat1_2." (PMID 35547764, 2022). "Among three Ras genes KRAS, NRAS, and HRAS, NRAS and HRAS mutations are more common in liver cancer." (PMID 33854636, 2021). "In liver cancer, activating mutations in KRAS and NRAS are found considerably more frequently than in HRAS." (PMID 26799184, 2016). "Co-expression with multiple potent oncogenes such as AKT and NRAS (G12V) could efficiently lead to the generation of liver cancer in male mice." (PMID 40520002, 2025). "Among the 5 liver cancer cell lines used in this study, 3 cell lines have oncogenic alterations known to activate the RAS/MAPK pathway (Huh7 and SNU387 with FGF19 amplifications; HepG2 with NRAS mutation)." (PMID 34458148, 2021). "Next, we tested the hypothesis that concomitant deletion of Yap and Taz would significantly suppress Akt/NRas-driven hepatocarcinogenesis by using Yap;Taz double KO mice in the Akt/NRas mouse liver cancer model." (PMID 33232824, 2021). "In order to induce liver cancer, mice were given hydrodynamic tail vein injections of plasmids to express constitutively active forms of AKT1 and NRas (SB/AKT/NRas), or AKT1 and c-Met (SB/AKT/c-Met)." (PMID 39254423, 2024). "In this study, we isolated and characterized two phenotypically distinct murine HCC clones derived from liver cancers after SB transposon-mediated integration of AKT and NRAS oncogenes." (PMID 35721518, 2022). "Given the widespread expression of SOX9 in fully developed Akt-YAP1 or Akt-NRAS CCA regions as well as poorly differentiated HCC regions, we delivered SB-STOP(flf)−Cas9-sg-Sox9 along with the Akt-YAP1 or Akt-NRAS plasmid into OPN-CreERT2 mice to induce liver cancer." (PMID 39273023, 2024).
multiple myeloma (22 papers, 2010 to 2025).